CD38 (CD38 molecule)
Diseases named in the same sentence as CD38 in open-access papers (continued):
Sharing a sentence is not in itself a finding about the gene and the disease.
COVID-19 (continued). "The results showed that most of the genes, as in the discovery set (except CD38, LYN, and ITGAX), were significantly upregulated in patients with severe COVID-19 (p < 0.05)." (PMID 36052061, 2022). "Our early COVID-19 case study revealed that both ICOS+PD-1+CD4+ TFHs and activated CD38+HLA-DR+ CD4+/CD8+ T cells appeared transiently in patient's blood at 3 days prior to recovery, suggesting involvement of T cells in the resolution of COVID-19." (PMID 35004764, 2021). "It has been reported that the activated CD38+HLA-DR+, CD8+ T cells, and CD38+HLA-DR+ CD4+ T cells that respond to virus infection are transiently increased in COVID-19 patients." (PMID 35011632, 2021). "The immune signature of COVID-19 ICU displayed a highly activated phenotype, particularly of T and NK cells characterized by a HLA-DR+CD38+ and CD127− phenotype." (PMID 34893580, 2021). "These genes were used as identifiers to classify the 126 patients based on the random forest algorithm, revealing that CD38, PTX3, and HSPA1A were able to classify patients into the correct groups and contribute specifically to COVID-19." (PMID 34899651, 2021). "In the COVID-19(−) virus group there was a high positive correlation between the percentage of RE-LYMP and proportion of CD4+ CD38+ cells (R = 0.7, p < 0.05) and between the percentage of RE-LYMP and GMF CD4+ CD38+ intensity (R = 0.8, p < 0.05)." (PMID 33419040, 2021). "The median proportion of CD8+ CD38+ cells and CD8+ CD38+ GMF intensity analysis showed the highest proportion in COVID-19(+) patients and significant differences between COVID-19(+) patients and the HC group." (PMID 33419040, 2021). "While cell numbers were higher in blood, higher frequencies of intermediate (CD14+CD16+) monocytes/macrophages, activated (HLADR+CD38+) and EM-like (CD27−CD45RA−) CD4+ and CD8+ T-cells were found in COVID-19 respiratory specimens compared to blood." (PMID 34462740, 2021). "Certainly, other molecules of the interferon pathways as MHC class I, CD38, BST-2 or CD123 should be analyzed in patients with COVID-19." (PMID 33825125, 2021). "In the COVID-19(+) group there was a significantly positive correlation between the percentage of RE-LYMP and CD4+ CD38+ lymphocytes (R = 0.5, p < 0.05) and between the percentage of RE-LYMP and GMF CD8+ CD45RO intensity (R = 0.7, p < 0.05)." (PMID 33419040, 2021). "Recent studies reported that, in many COVID-19 patients, CD8+ T cells presented the hyperactivation feature, including high levels of markers for cytotoxicity, increased numbers of CD38+HLA-DR+ activated population, and more Ki67+ proliferating cells." (PMID 34618873, 2021). "MIS-C had higher frequencies of HLA-DR+CD38+ CD4+ and CD8+ T cells compared to pediatric COVID-19, again rivaling or exceeding that observed in adult COVID-19." (PMID 33653907, 2021). "Overall the frequencies of CD38+ and HLA-DR+CD38+ memory CD4+ and CD8+ T cells in severe COVID-19 were elevated compared to HD (p<0.01 for all cases), and frequency of HLA-DR+ CD4+ and CD8+ T cells was also directly associated with APACHE III scores." (PMID 32669287, 2020). "The expression profiles for HLA-DR, CD38, PD-1, and CD71 were also determined for tetramer+ A2/S269+CD8+ T cells from the COVID-19 patients." (PMID 32913053, 2020). "CD8+ T cells from COVID-19 patients have a very marked activation phenotype with an increase in CD69, CD38, CD137, and CD44, especially in critically ill patients." (PMID 33193331, 2020). "Despite this, COVID-19 patients exhibited decreased frequencies of naive but elevated frequencies of effector TEMRA and HLA-DR+CD38+ CD8+ T cells." (PMID 32943497, 2020). "Overall, we observed a strong activation of T cells in COVID-19 and malaria with an increased expression of both early (CD69+) and late (HLA-DR+CD38+) activation markers as well as the co-stimulatory receptor CD226." (PMID 32983106, 2020).
COVID-19 (continued). "There were increased levels of CD69 and HLA-DR/CD38 co-expression on CD8+ and CD4+ T cells in both COVID-19 and malaria patients compared to healthy controls which is characteristic for acute infections." (PMID 32983106, 2020). "Nevertheless, the frequency of the KI67+ or CD38+HLA-DR+ CD8 and CD4 T cell responses in COVID-19 patients was similar in magnitude to those of other acute viral infections or live attenuated vaccines in humans." (PMID 32669297, 2020). "COVID-19 patients show a substantial reduction in the numbers of peripheral CD4 and CD8 T cells, with the remaining cells exhibiting a hyperactivated status (CD38+ HLA-DR+) and are enriched for pro-inflammatory C-C chemokine receptor 6 (CCR6+) Th17 T cells." (PMID 33302366, 2020). "T cells of patients with COVID-19 and acute malaria showed high frequencies of the activation markers CD69 and HLA-DR/CD38 as well as high frequencies of the inhibitory receptors LAG-3 and TIM-3." (PMID 32983106, 2020). "CD8+ T-cells in COVID-19 patients also showed activated phenotypes with higher expression of CD69, CD38 and CD44." (PMID 34676125, 2020). "In this context, it is relevant to note the presence of SARS-CoV-2-reactive CD4+ T cells in recovered COVID-19 patients 65, 66, and that the development of SARS-CoV-2 reactive CD38+/HLA-DR+/CD4+ T cells strongly correlates with a positive clinical outcome." (PMID 33173418, 2020). "Interestingly, we found that COVID-19 patients with neutrophilia, lymphopenia and a more pronounced alteration in the biochemical parameters associated to inflammation had a higher percentage of CD4+ T cells with expression of activation markers HLA-DR and CD38." (PMID 33324414, 2020). "For a description of the activation status, we assessed the frequencies of CD69 and HLA-DR/CD38 on CD8+ and CD4+ T cells in COVID-19 and malaria patients as well as in healthy controls." (PMID 32983106, 2020). "These CD4+ T-cells in COVID-19 patients have higher expression of CD69, CD38 and CD44 compared with healthy controls, indicating their activated status." (PMID 34676125, 2020). "Despite this, the functionality of these T cells (Ki-67+, IFN-γ+, CD69+, CD38+ etc.)did not decrease with culture in UN or COVID-19+." (PMID 40698364, 2025). "In addition, there was dysregulated NAD+ metabolism in CD38+HLA-DR+ T cells via scRNA-seq, accompanied by elevated adenosine and decreased NAD+ levels in serums from COVID-19 patients." (PMID 40370439, 2025). "CD38, which is also recognized as a pivotal NAD+ hydrolase, may play a significant role in the immunosuppressive environment characteristic of COVID-19 through its enzymatic conversion of NAD+ to adenosine." (PMID 40370439, 2025). "Markers of activation CD38 and CD69 were more highly expressed on COVID-19 patient NK cells." (PMID 38578283, 2024). "In addition, immunohistochemical staining revealed severe infiltration of CD68+ (macrophages), CD38+ (activated B cells), and CD138+ (plasma cells) in the interstitial compartments of testis tissue of the COVID-19 group." (PMID 39866583, 2024). "Similarly, Mathew and colleagues (2020) observed that among patients with COVID-19, activation levels of CD8 and CD4 T cells (via HLA-DR and CD38 co-expression) were similar to the antiviral responses that have been observed for other infections." (PMID 36675642, 2023). "CD38-generated metabolites, including ADPR, nicotinamide, cADPR, and NAADP, stimulate several pathways that finally aggravate a hyperinflammatory profile typical in patients with COVID-19." (PMID 36675642, 2023). "In the context of COVID-19, CD38 expression is widely induced across CD8, CD4, Treg, and plasma cells, suggesting that CD38 expression across these disparate populations may either be driven by a central factor or interaction between these cell types." (PMID 36669118, 2023).
COVID-19 (continued). "The evolution of this cell population (HLA-DR T cells without considering the expression of CD38) during the follow-up of COVID-19 patients has not been studied previously." (PMID 38035104, 2023). "Moreover, CD38 and HLA-DR were differentially expressed by CD4+ and CD8+ T cell subsets in BALF-MC and in PBMC among SARS-CoV-2-infected patients who died from COVID-19 (p < 0.05)." (PMID 36986364, 2023). "Comparing COVID-19 and controls at the level of MFI for each subject within each MC and each subset revealed expression patterns highly comparable to CAP, such as decreased HLA-DR and CD11c, and increased PD-L1, PD-1, CD95/Fas, CD38 and CXCR5." (PMID 38077404, 2023). "Thus, overexpression of CD38 and depletion of NAD+ could both be considered common features of aging with a consequent overload of Ca2+, diminished mitochondrial function, and chronic inflammation predisposing elderly individuals to severe infections with COVID-19." (PMID 36675642, 2023). "CD38 interacts with its counterreceptor, CD31 (endothelial/platelet cell adhesion molecule-1), which has two major consequences: thrombosis and lymphopenia, which are both COVID-19 disease severity predictors." (PMID 36675642, 2023). "However, some studies demonstrated that these NK cells overexpressed several markers related to a dysfunctional phenotype in severe COVID-19, like CD39, PD-1, NKG2A, DUSP2, CD69, CD38, LAG-3 and TIM-3." (PMID 37311004, 2023). "In blood from hospitalized COVID-19 patients, a similar proportion of activated HELIOS+ CD8 T cells and HELIOS- counterparts were detected as indicated by positive staining for Ki-67 and CD38." (PMID 38187391, 2023). "In this regard, alone or combined expression level of PD1 on CD4+ T-cells as well as the expression level of CD38 on CD8+ T-cells could be potential biomarkers in the prediction of disease severity and outcome in patients with COVID-19." (PMID 35655192, 2022). "This suggests that the remaining CpGs (annotated in genes such as CCDC61, CD38, FAM38A, LAT, TREX1 or NFAT5, among others) differentially contribute to similarities between COVID-19 progression and SADs, some of them regulating the activation and differentiation of T and B lymphocytes." (PMID 35933486, 2022). "Compared to individuals tested negative for SARS-CoV-2, COVID-19 patients show a specific B cell population expressing cell surface marker CD27+CD38+." (PMID 36369012, 2022). "Currently, we have shown that vitamin D supplementation could effectively decrease the relative numbers of activated CD38++CD27 transitional B cells and ‘naïve’ B cells in patients with acute COVID-19." (PMID 35807783, 2022). "Indeed, upregulation of CD25 and CD38 expression is also observed in all differentiation stages of CD8+, Vδ1+, and Vδ2+ T lymphocytes in COVID-19 patients, except in Vδ2+ TEMRA, compared to recovered and healthy subjects." (PMID 36359845, 2022). "Furthermore, the expression level of HLA-DR and CD38 on CD4+ and CD8+ T cells in peripheral blood significantly increased in patients with COVID-19, and the maximum values were found in patients with a poor disease outcome." (PMID 35632823, 2022). "A significant increase in HLA-DR+CD38+ non-naïve CD8 T cells has also been reported in hospitalized COVID-19 patients compared to HS and recovered donors, although many patients showed little evidence of T cell activation in the blood." (PMID 35898494, 2022). "Among the overlapping cell types, we found that 49% of ADT-annotated activated effector T cells cluster (HLA-DR+CD38+, ADT cluster #15) are overlapped with GEX dividing T/NK cluster, indicating expression of both HLADRA/CD38 and MKI67 marks a unique T cell subset in COVID-19." (PMID 35064122, 2022). "Concerning the activated CD8+ T cell population expressing CD38 and HLA-DR, the levels were elevated compared to healthy controls and were sustained for more than 6 weeks, whereas the CD4+ T cells decreased over time within the COVID-19 patients." (PMID 36003367, 2022).
COVID-19 (continued). "We found a significantly lower expression of CD159/NKG2A on CD8+ and NK cells and a significantly higher expression of CD38 on CD8+ cells on admission in COVID-19 non-survivors." (PMID 35392095, 2022). "In addition, decreased CD38+HLA-DR− and increased CD38−HLA-DR− CD4 naive T cells occurred in individuals recovered from severe and critical COVID-19 (Bonferroni-adjusted P-value range 0.02–1.46 × 10−4)." (PMID 36433939, 2022). "CD38 plays an important role in viral infections, including AIDS and COVID-19." (PMID 36077708, 2022). "In contrast to the CD4 T cells, we did not observe a correlation between CD38+HLA-DR+ cells and PD-1+ cells in COVID-19 patients, probably suggesting that PD-1 expression on CD8 T cells is more a marker of exhaustion than of activation." (PMID 33777054, 2021). "Next, in these three groups: COVID-19(+), HC, and COVID-19(−) virus group we analyzed median proportion and GMF intensity of: CD25, CD45RO, CD38, and HLA-DR markers on CD4 and CD8 lymphocytes T. We compared the differences in expression of these antigens between these three groups." (PMID 33419040, 2021). "Moreover, in these patients, the memory maturation profile and expression of other activation markers (such as CD38, Ki67, and PD-1) in M. tuberculosis–specific CD4+ T cells were similar between COVID-19 patients and hospitalized non–COVID-19 controls." (PMID 33945513, 2021). "We detected an increased CD38 expression level in our patient affected by COVID-19 and a coexistent HD but not in the other patient that was affected by COVID-19 and a coexistent indolent CLL." (PMID 33794925, 2021). "In particular, in the patient with COVID-19 and HD the expressions of the CD38 and of the IFIT3 genes are strongly increased, while in the patient with COVID-19 and CLL they are both normally expressed at a level comparable to that observed in the COVID-19 patients without the Low T3 syndrome." (PMID 33794925, 2021). "We found an expansion in the CD38+HLA-DR+ subset in all the non-naïve CD4 T cell subsets from COVID-19 patients, more significantly in the severe group." (PMID 33777054, 2021). "We found higher frequencies of neutrophils, intermediate CD14+CD16+monocytes, activated HLA-DR+CD38+, EM-like CD4+ and CD8+ T-cells in COVID-19 respiratory compared to blood samples, and similar immune responses with dexamethasone (with/without remdesivir) treatment." (PMID 34462740, 2021). "Frequencies of activated (HLA-DR+CD38+ or Ki67+) CD8+ and CD4+ T cells and activated CX3CR1+ CD8+ T cells remained elevated in MIS-C even when compared to the severe subgroup of pediatric COVID-19." (PMID 33653907, 2021). "In the study, we showed that in the group of COVID-19(−) virus there were the strongest positive correlations RE-LYMP with CD38 and HLA-DR markers in both CD4 and CD8+ cells without correlations with markers CD25 and CD45RO." (PMID 33419040, 2021). "As expected, the expression of HLA-DR, CD38, and Ki67 on SARS-CoV-2–responding CD4+ T cells was significantly higher in COVID-19 cases compared with non–COVID-19 controls (P = 0.005, P < 0.0001, and P = 0.004, respectively), likely reflecting ongoing viral replication." (PMID 33945513, 2021). "Furthermore, low frequencies of CD45RA-PD-1+CXCR5+cTfh cells were also observed, but elevated frequencies of activated cTfh (CD38+ICOS+) cells were positively correlated with anti-SARS-CoV-2 IgM and IgG titers in hospitalized COVID-19 patients." (PMID 34603308, 2021). "Early pathological findings of COVID-19 patients with ARDS, showed not only reduced counts of peripheral CD4+ and CD8+ T cells, but that remaining T cells were found in a hyperactivated state, with high proportions of HLA-DR and CD38 double-positive fractions." (PMID 33013871, 2020). "This upregulation of HLA-DR/CD38 on T cells co-expressing PD1 and LAG-3 and PD1 and TIM-3 could be observed on both CD8+ and CD4+ T cells in COVID-19 and malaria patients." (PMID 32983106, 2020).
COVID-19 (continued). "Frequencies of KI67+ or CD38+HLA-DR+ non-naïve CD4 T cells were increased in COVID-19 patients; however, this change was not equivalent across all CD4 T cell subsets." (PMID 32669297, 2020). "The early prominence of activated CD38+HLA-DR+ and CD38+PD-1+ CD8+ T cells is associated with survival; the loss of expansion of SARS-CoV-2-specific immunity and the prolonged presence of CD38+HLA-DR+ and CD38+PD-1+ CD8+ T cells are characteristics of fatal COVID-19." (PMID 33362779, 2020). "In addition, the frequencies of HLA-DR+CD38+ CD4+ and CD8+ T cells correlated with the proportion of plasmablasts in moderate and severe COVID-19+ individuals." (PMID 32669287, 2020). "There was a significant increase in KI67+ and also HLA-DR+CD38+ non-naïve CD8 T cells in COVID-19 patients relative to HDs or RDs." (PMID 32669297, 2020). "By further elucidating the function of the CD38-NAD+ metabolic axis in immune metabolism and signaling, we can explore novel therapeutic strategies to modulate immune responses, enhance anti-infective capabilities, and potentially offer new avenues for treating COVID-19 and other diseases." (PMID 39852780, 2024). "Accordingly, the T-cell subset expressing activation markers (CD38 and HLA-DR), more than the nonactivated subset, allowed appreciation of these T-cell features in our COVID-19 patient group with a significantly increased clonality (reciprocal of diversity) and SARS-CoV-2–associated repertoire size." (PMID 37787611, 2024). "No significant changes in CD4+ T cell activation, defined by HLA-DR and CD38 expression, were detected; however, both pregnant and nonpregnant women had significant increases in polyfunctional CD4+ T cells expressing granzymes and perforin during acute COVID-19." (PMID 37036008, 2023). "To investigate if B cells from COVID-19 and HIV-1+ patients exhibited distinct transcriptional signatures, we performed integration and clustering on B cell and plasmablast populations (central and bottom clusters in UMAP), identified by upregulation of CD19/MS4A1 and CD38 respectively." (PMID 36992700, 2023). "In a cohort of 43 COVID-19 patients and 25 healthy controls, circulating MAIT cells displayed reduced frequency and an activated phenotype in individuals with COVID-19, regardless of disease severity, as characterised by high expression of IL-17A, TNFα, CD38, CD69 and HLA-DR." (PMID 34050887, 2022). "Together, we see an improved outcome in our HD cohort with less ICU admissions, which might be attributed to a chronic inflammatory state and increased frequencies of CD38+CD8+ memory and CD161+CD8+ T cells, both having a high cytotoxic activity to limit COVID-19 severity." (PMID 35265078, 2022). "Surprisingly, a recent hypothesis was raised that CD38, together with NADase, are also involved in the response to severe acute respiratory syndrome coronavirus 2 (SARS-CoV-2), which is responsible for the COVID-19 pandemic." (PMID 36012131, 2022). "Besides, a positive correlation between the percentages of CD8+CD38+HLA-DR+ T cells and HLA-DR+NK cells (r=0.529, p<0.0001) was demonstrated in COVID-19 patients but not in the vaccinated individuals." (PMID 35898494, 2022). "In COVID-19, circulating CD27+CD38+CD138+ B cells not only contained high levels of Ki67 in the cytoplasm but also expressed the activation marker CD95 on their membrane, which could indicate a recent migration of B cells from the germinal centers of lymphoid tissue." (PMID 35632823, 2022). "Another report that investigated BAL samples from COVID-19 patients demonstrated that atypical lymphocytes in BAL samples were virtually all CD3-positive T cells, and a significant proportion of T cells (40–80%) in BAL samples expressed activation markers such as CD38, HLA-DR and CD25." (PMID 34767614, 2021).